TAF4 (TATA-box binding protein associated factor 4)
Description:
The TFIID basal transcription factor complex plays a major role in the initiation of RNA polymerase II (Pol II)-dependent transcription. TFIID recognizes and binds promoters with or without a TATA box via its subunit TBP, a TATA-box-binding protein, and promotes assembly of the pre-initiation complex (PIC). The TFIID complex consists of TBP and TBP-associated factors (TAFs), including TAF1, TAF2, TAF3, TAF4, TAF5, TAF6, TAF7, TAF8, TAF9, TAF10, TAF11, TAF12 and TAF13. TAF4 may maintain an association between the TFIID and TFIIA complexes, while bound to the promoter, together with TBP, during PIC assembly. Potentiates transcriptional activation by the AF-2S of the retinoic acid, vitamin D3 and thyroid hormone.
Synonyms: TAF(II)130; TAFII-130; TAFII130; TAF(II)135; TAFII-135; TAFII135; TAF2C; TAF2C1; TAF4A; MRD73
Tractability: Small molecule: a structure with a bound ligand is known. PROTAC: ubiquitination databases record sites on it; its protein half-life has been measured.
Gene: Protein-coding gene on chromosome 20 (61,953,469 to 62,065,881, reverse strand). Ensembl gene ENSG00000130699.
Subcellular location: Nucleus
Subcellular location (Human Protein Atlas): Nucleoplasm; Cytosol; Endoplasmic reticulum
Pathways (Reactome):
Gene expression (Transcription): RNA Polymerase II Pre-transcription Events; RNA Polymerase II Promoter Escape; RNA Polymerase II Transcription Initiation; RNA Polymerase II Transcription Initiation And Promoter Clearance; RNA Polymerase II Transcription Pre-Initiation And Promoter Opening
Disease: HIV Transcription Initiation; RNA Polymerase II HIV Promoter Escape; Transcription of the HIV genome
Gene Ontology:
Molecular function: aryl hydrocarbon receptor binding; core promoter sequence-specific DNA binding; protein binding; RNA polymerase II general transcription initiation factor activity; DNA binding; protein heterodimerization activity; RNA polymerase II-specific DNA-binding transcription factor binding
Biological process: DNA-templated transcription initiation; mRNA transcription by RNA polymerase II; positive regulation of transcription initiation by RNA polymerase II; regulation of transcription by RNA polymerase II; RNA polymerase II preinitiation complex assembly; transcription initiation at RNA polymerase II promoter; positive regulation of DNA-templated transcription; regulation of DNA repair; transcription by RNA polymerase II; DNA-templated transcription
Cellular component: chromatin; MLL1 complex; nucleoplasm; nucleus; protein-containing complex; transcription factor TFIID complex; transcription factor TFTC complex
Genetic constraint (gnomAD): Loss-of-function variants: 9 observed, 76.75 expected, observed/expected ratio (o/e) 0.12, 90% interval 0.07 to 0.2. The synonymous counts are far from expectation, so gnomAD's model fits this gene poorly and the ratio says little. Missense variants: 958 observed, 1,028.7 expected, observed/expected ratio (o/e) 0.93, 90% interval 0.88 to 0.98. Synonymous variants: 600 observed, 460.34 expected, observed/expected ratio (o/e) 1.3, 90% interval 1.22 to 1.39.
Homologues: Orthologues: chimpanzee TAF4 (99% identical), macaque TAF4 (99% identical), mouse Taf4 (82% identical), dog TAF4 (82% identical), pig TAF4 (81% identical), rat Taf4 (80% identical), tropical clawed frog taf4 (63% identical), guinea pig TAF4 (53% identical), zebrafish taf4a (43% identical), Caenorhabditis elegans taf-4 (13% identical). Paralogues in human: TAF4B (30% identical).
Diseases named in the same sentence as TAF4 in open-access papers:
TAF4 is named in the same sentence as 16 diseases in open-access papers, as found by Europe PMC text mining. Sharing a sentence is not in itself a finding about the gene and the disease. The quoted sentences say what the papers report.
autism (2 papers, 2021 to 2023). Persistent deficits in social interaction and communication and interaction as well as a markedly restricted repertoire of activity and interest as well as repetitive patterns of behavior. "Furthermore, TAF4 has been previously associated with autism and a missense mutation in TAF4 (A124P) was identified in two autistic individuals from two different families (Families 4 and 21) in our study." (PMID 36702863, 2023).
melanoma (2 papers, 2014 to 2016). A malignant, usually aggressive tumor composed of atypical, neoplastic melanocytes. "Altogether, our data using TAF4 gain- and loss-of function studies allow the conclusion that melanomas have properties of stem cells and exhibit multilineage differentiation potential." (PMID 25244017, 2014). "Herein we show that malignantly transformed cells, melanoma in particular, represent a unique model where both, canonical and alternative TAF4 isoforms, are expressed at comparable levels providing an attractive context for manipulating cancer cells in vitro." (PMID 27499390, 2016). "Taken together, targeted AS of TAF4 provides a unique strategy for generation of iMels and recapitulating stages of melanoma progression." (PMID 27499390, 2016). "All these data further argued that hTAF4-TAFH rendered TAF4 to control chondrogenic differentiation in melanoma cells." (PMID 27499390, 2016). "All in all, data of melanoma cell reprogramming by enforced expression of TAF4 evidenced the fast induction of multipotent features in tumours just by altering the hTAF4-TAFH activity levels in cells." (PMID 27499390, 2016). "In contrast, ectopic expression of the canonical TAF4 in melanoma cells leads to the up-regulation of pluripotency markers KLF4, OCT4 and NANOG." (PMID 25244017, 2014). "Through regulation of the TAF4 ASVs expression balance in melanoma, it is possible to get melanoma populations with strong multipotent properties or drive cells to differentiate." (PMID 25244017, 2014). "Our recent data demonstrate that reduced expression of full-length TAF4 by RNAi leads to the enhanced motility of normal dermal fibroblasts and malignant melanoma cells." (PMID 25244017, 2014). "In contrast, cancer cells, such as melanoma, express both canonical and other isoforms of TAF4 at high levels, thereby raising the question of the differentiation potential of tumour cells." (PMID 25244017, 2014). "In contrast, transient over-expression of canonical TAF4 diminishes the invasion potential of the melanoma cells." (PMID 25244017, 2014). "To assess whether AS of TAF4 exons V, VI and VII encoding the hTAF4-TAFH is prevailing in cells of neural crest (NC) origin, we examined the expression of TAF4 ASVs in facial dermal fibroblasts, melanocytes and melanomas." (PMID 27499390, 2016). "Overexpression of TAF4 resulted as expected in the heightened levels of TAF4 protein and significantly increased TAF4_v1 mRNA expression, and brought along phenotypic changes of SkMel28 melanoma towards cells with drastically reduced invasive potential." (PMID 27499390, 2016). "Upon TAFH RNAi, silencing of TAFH_v1 mRNAs both in fibroblasts and melanoma SkMel28 and WM 266-4 cells promoted the expression of transcripts encoding isoforms without hTAF4-TAFH that was also verified by changed patterns of TAF4 isoform expression." (PMID 27499390, 2016). "To further assess the role of hTAF4-TAFH activity in cell reprogramming, we investigated whether melanoma cells were amenable to reprogramming towards induced cancer stem cell (iCSC)-like cells by using forced expression of TAF4." (PMID 27499390, 2016). "On the other hand, enforced expression of TAF4 promoted expression of pluripotency- associated KLF4, OCT4 and NANOG, and NC-related MSX2, PAX7, SOX10 and SNAI1, reaffirming the critical role of hTAF4-TAFH activity in the maintaining of multipotency in melanoma cells." (PMID 27499390, 2016). "Reprogramming of melanoma cells by manipulation with hTAF4-TAFH activity upon TAFH RNAi enforces cell differentiation towards chondrogenic pathway, whereas ectoptic expression of TAF4 results in enhanced multipotency and neural crest-like features in melanoma cells." (PMID 27499390, 2016).
melanoma (continued). "Upon TAF4 RNAi, a change in expression from canonical to alternative TAF4 isoforms with disturbed hTAF4–TAFH activity is observed, whereas removal of hTAF4–TAFH activity accelerates differentiation of melanoma cells along chondrogenic, adipogenic and neural lineages." (PMID 25244017, 2014).
breast carcinoma (1 paper, 2013). "Male and female breast cancers displayed remarkably different landscapes of candidate drivers, as only two candidate drivers were found in common (TAF4 and CD164)." (PMID 24194916, 2013).
embryonic carcinoma (1 paper, 2013). "In addition to global gene silencing that has been evidenced to occur during ES cell differentiation, proteasome-dependent TAF4 degradation was observed in F9 embryonic carcinoma cells in response to retinoic acid-induced differentiation." (PMID 24098348, 2013).
Hypoglycemia (1 paper, 2014). A decreased concentration of glucose in the blood. "TAF4 knockout in post-natal hepatocytes therefore causes severe liver malfunction, hypoglycemia, and dysfunctional bile and lipid transport and metabolism." (PMID 25209997, 2014). "PAS staining revealed a lack of glycogen in TAF4 knockouts, which along with hypoglycemia shows defective carbohydrate metabolism in Tafa4hep−/− mice." (PMID 25209997, 2014).
intestinal tumors (1 paper, 2023). "Taf4 loss both in non-tumoral gut mucosa and in intestinal tumors therefore led to an altered immune environment." (PMID 36639541, 2023).
Obesity (1 paper, 2013). Accumulation of substantial excess body fat. "Our data also reveals the potential role of TAF4 isoforms in delaying adipogenic differentiation of hMSCs and thus contributes to the understanding of the mechanisms of obesity." (PMID 24098348, 2013).
ovarian carcinoma (1 paper, 2024). A malignant neoplasm originating from the surface ovarian epithelium. "TAF4, a transcription initiation factor, when overexpressed, is implicated in ovarian cancer by playing a role in dedifferentiation that promotes metastasis and chemoresistance." (PMID 38896472, 2024).
cancer (4 papers, 2014 to 2024). A tumor composed of atypical neoplastic, often pleomorphic cells that invade other tissues. "In this review, we focus on the role of TATA-box associated factor 4 (TAF4) and its functional isoforms generated by alternative splicing in controlling lineage-specific differentiation of normal mesenchymal stem cells and cancer stem cells." (PMID 25244017, 2014). "In conclusion, a more detailed understanding is required to clarify the role of TAF4 in the sequence of events driving the generation of iMels and cancer progression." (PMID 27499390, 2016). "Altogether, our studies identify TAF4 as a critical modulator of cell differentiation and metastatic spread of cancer." (PMID 25244017, 2014). "Thus, pluripotency and differentiation status of normal and cancer cells can be controlled by TAF4 ASV expression." (PMID 25244017, 2014). "Interestingly, many of the identified DMRs within the signature are localized close to genes already associated with cancer, such as MEF2C and TAF4." (PMID 25261372, 2014). "Data presented here allow us to conclude that targeting AS of TAF4 affects the entire TFIID complex, providing a unique model system to induce iMels and reprogram tumour cells to less or more aggressive cancer phenotypes." (PMID 27499390, 2016). "Simultaneous presence of TAF4 isoforms with high and low hTAF4-TAFH activities in normal cells and in cancer suggests that dominance of any of these forms is likely to have dramatic effects upon development and in tumour progression." (PMID 27499390, 2016). "Our anti-TAF2 antibody was able to immunoprecipitate endogenous TAF2, as well as core subunits of the TFIID complex, including TBP, TAF4, TAF5, TAF6, and TAF7, in nuclear extracts from colorectal HCT116, embryonic kidney HEK-293, and ovarian A2780 cancer lines." (PMID 38773077, 2024).
tumour (3 papers, 2014 to 2023). "In a cohort of males (n > 10 in each group), Taf4 loss in Taf4IEC::Apc+/Δ14 mice reduced overall survival and aggravated tumor burden compared to Apc+/Δ14 mice." (PMID 36639541, 2023). "Several lines of evidence suggest that the increased PRC2 activity seen upon Taf4 inactivation may be linked to the altered mucosal and tumor immune microenvironment." (PMID 36639541, 2023). "Together these results revealed a novel facet of Taf4 function in influencing the immune microenvironment in both normal mucosal tissue and in the tumor context." (PMID 36639541, 2023). "In summary, the detailed understanding of TAF4 proteomics in different cellular contexts, including tumour cells, will clearly be of immense benefit for future prospects of cell-directed therapeutics." (PMID 25244017, 2014). "Since Taf4 inactivation led to increased PRC2 activity in crypt SCs, that in enteroids resulted in the increased pool of undifferentiated cells, we asked if this alteration may affect intestinal tumorigenesis in the tumor prone model of Apc+/Δ14 mice." (PMID 36639541, 2023).
TAF4 also shares sentences with these, for which no sentence is quoted: colon cancer (1 paper); graft versus host disease (1); HIV-1 infection (1); Infertility (1); Intellectual disability (1); papilloma (1).